ENSG00000252689
Synonyms: LOC124900508
Gene: Small nucleolar RNA gene on chromosome Y (16,138,248 to 16,138,379, reverse strand). Ensembl gene ENSG00000252689.
Gene Ontology:
Biological process: RNA processing
Cellular component: nucleolus
Homologues: Orthologues: mouse Gm24615 (65% identical). Paralogues in human: SNORA20 (83% identical), SNORA20B (83% identical).